TYW1 (tRNA-yW synthesizing protein 1 homolog)
Description:
Involved in the biosynthesis of wybutosine, a hyper modified guanosine with a tricyclic base located at position 37 of eukaryotic phenylalanine tRNA (tRNA(Phe)) that contributes to maintenance of the translational reading frame. Catalyzes the condensation of N-methylguanine with 2 carbon atoms from pyruvate to form the tricyclic 4-demethylwyosine, an intermediate in wybutosine biosynthesis.
Synonyms: RSAFD1; FLJ10900; MGC23001; MGC60291; YPL207W; TYW1A
Tractability: PROTAC: ubiquitination databases record sites on it.
Gene: Protein-coding gene on chromosome 7 (66,995,173 to 67,239,521, forward strand). Ensembl gene ENSG00000198874.
Subcellular location (Human Protein Atlas): Nucleoli; Nucleoli rim; Nucleoplasm
Pathways (Reactome):
Metabolism of RNA: Synthesis of wybutosine at G37 of tRNA(Phe)
Gene Ontology:
Molecular function: 4 iron, 4 sulfur cluster binding; catalytic activity; FMN binding; iron-sulfur cluster binding; tRNA-4-demethylwyosine synthase activity
Biological process: wybutosine biosynthetic process; tRNA processing
Genetic constraint (gnomAD): Loss-of-function variants: 46 observed, 95.19 expected, observed/expected ratio (o/e) 0.48, 90% interval 0.38 to 0.62. The upper end of that interval is the gene's LOEUF score, 0.62, which puts it in group 2 of 6, group 1 being the genes least tolerant of losing a copy. Missense variants: 678 observed, 902.26 expected, observed/expected ratio (o/e) 0.75, 90% interval 0.7 to 0.8. Synonymous variants: 274 observed, 318.14 expected, observed/expected ratio (o/e) 0.86, 90% interval 0.78 to 0.95.
Homologues: Orthologues: macaque TYW1 (97% identical), rat Tyw1 (82% identical), mouse Tyw1 (80% identical), tropical clawed frog tyw1 (72% identical), zebrafish tyw1 (69% identical). Paralogues in human: TYW1B (87% identical).
Diseases named in the same sentence as TYW1 in open-access papers:
TYW1 is named in the same sentence as 5 diseases in open-access papers, as found by Europe PMC text mining. Sharing a sentence is not in itself a finding about the gene and the disease. The quoted sentences say what the papers report.
malaria (1 paper, 2016). Malaria is a serious and sometimes fatal disease caused by a parasite that commonly infects a certain type of mosquito which feeds on humans. "Plasmodium orthologues of mitochondrial iron importers mrs3 and mrs4 remain to be identified, as does the putative role of the Plasmodium orthologue of TYW1 and other iron–sulfur cluster containing proteins in mediating protection against high iron toxicity in malaria parasites." (PMID 26786069, 2016).
cancer (2 papers, 2020 to 2025). A tumor composed of atypical neoplastic, often pleomorphic cells that invade other tissues. "While the roles of TRMT2B and TYW1 in cancer are not yet defined, their significant coefficients in our model suggest potential functional importance that warrants further study." (PMID 40561176, 2025).
TYW1 also shares sentences with these, for which no sentence is quoted: colorectal cancer (1 paper); leukemia (1); tumour (1).